SMAD4 (SMAD family member 4)
Diseases named in the same sentence as SMAD4 in open-access papers (continued):
Sharing a sentence is not in itself a finding about the gene and the disease.
juvenile polyposis syndrome (continued). "SMAD4 mutations lead to the combined syndrome of juvenile polyposis (JP) and HHT (JP-HHT)." (PMID 23805858, 2013). "Other rare colonic polyposis syndromes for which the genetic basis is known include Cowden syndrome (mutations in PTEN), juvenile polyposis (mutations in SMAD4 or BMPR1A), hereditary mixed polyposis syndrome (mutation in GREM1), and MUTYH-associated polyposis (biallelic mutations in MUTYH)." (PMID 23805267, 2013). "The manifestation of juvenile polyposis is preconditioned by mutations in SMAD4 and BMPR1A genes." (PMID 23724922, 2013). "On of them, SMAD4, cause juvenile polyposis when mutated in germline cells." (PMID 20459617, 2010). "Similarly, germline SMAD4 mutations are responsible for a subset of patients affected by juvenile polyposis syndrome, an autosomal dominant intestinal cancer syndrome." (PMID 19014666, 2008). "Juvenile polyposis syndrome (JPS) belongs to the autosomal dominant hamartomatous polyposis syndromes involving variants in the SMAD4 and BMPR1A genes." (PMID 41226105, 2025). "In conclusion, our study delved into the intricate genetic interplay associated with Smad4 knock-out in juvenile polyposis syndrome (JPS) using collaborative cross (CC) mice, a genetically diverse model." (PMID 38891999, 2024). "Juvenile polyposis syndrome (JPS) is an autosomal dominant condition associated GPVs in SMAD4 or BMPR1A." (PMID 37258796, 2023). "Juvenile polyposis syndrome (JPS) is a hereditary gastrointestinal polyposis syndrome where SMAD4 germline mutation is found in 20% of cases." (PMID 37377893, 2023). "SMAD4 loss-of-function mutations are associated with juvenile polyposis syndrome (JPS) and a combined JPS-hereditary hemorrhagic telangiectasia (HHT) known as “JPS-HHT syndrome”, and some affected individuals present with aortic dilatation." (PMID 35517795, 2022). "Germline mutations in SMAD4 can lead to juvenile polyposis syndrome (JPS), characterized by benign tumor formation in the gastrointestinal tract and an increased risk of gastrointestinal malignancies." (PMID 33509126, 2021). "The SMAD4 germline variant is the most frequently recognized in juvenile polyposis syndrome (JPS), along with the BMPR1A germline variant." (PMID 34476650, 2021). "Juvenile polyposis syndrome (JPS) is a rare disorder characterized by the presence of multiple juvenile polyps in the gastrointestinal tract, and germline mutations in SMAD4 or BMPR1A." (PMID 32487124, 2020). "Indeed, the loss of BMPR2 and SMAD4 expression has been reported in sporadic CRC, whereas germline mutations of BMPR1 and SMAD4 genes have been demonstrated to enhance the susceptibility to develop juvenile polyposis, supporting that TGF-β signaling inactivation plays a key role in CRC development." (PMID 31591478, 2020). "In addition, mutations in SMAD4 (encoding the transcription factor Smad4) have been described in a subset of HHT patients which present a juvenile polyposis/HHT overlap syndrome (JP-HHT, OMIM #175050) but the frequency of these mutations does not exceed 2% of the HHT patient population." (PMID 31910860, 2020). "Individuals with juvenile polyposis syndrome (JPS) are carriers of mutations in crucial components of the BMP pathway such as the BMP receptor 1a (BMPR1a) or the downstream signaling molecule SMAD4." (PMID 32486027, 2020). "A germline mutation of SMAD4 can cause juvenile polyposis syndrome (JPS) which is associated with CRC 27,29." (PMID 28989593, 2017). "Herein, we report a child with juvenile polyposis syndrome (JPS) with a novel mutation in the SMAD4 gene." (PMID 28428902, 2017). "Another important hereditary condition is the juvenile polyposis syndrome (JPS) which is inherited as an autosomal dominant due to specific mutation in the BMPR1A gene or the SMAD4 gene." (PMID 23737765, 2013).
juvenile polyposis syndrome (continued). "We report the case of a 10-year-old boy with hereditary hemorrhagic telangiectasia (HHT) and a family history of SMAD4-related juvenile polyposis syndrome (JPS), presenting with hypoferritinaemia unresponsive to oral supplementation." (PMID 42110114, 2026). "Other genes with mutations contributing to some cases of HHT include MADH4, which encodes SMAD4 (leading to the juvenile polyposis-HHT phenotype), and GDF2, which encodes BMP9, a ligand of ALK1 (HHT5 phenotype)." (PMID 41303195, 2025). "For example, Smad4+/- mice spontaneously developed juvenile polyposis (JP) at 1.5 years, and invasive adenocarcinoma when crossed with Apc∆716/+ mice." (PMID 40348815, 2025). "Our study provides a comprehensive understanding of the intricate genetic factors at play in Smad4 knock-out, offering valuable insights into potential therapeutic targets for juvenile polyposis and related diseases." (PMID 38891999, 2024). "The deletion region contains the TCF4 and SMAD4 genes, whose haploinsufficiency causes the causative genes of Pitt-Hopkins syndrome (PTHS) and juvenile polyposis/hereditary hemorrhagic telangiectasia (JPHT or JPHHT), respectively." (PMID 37521594, 2023). "Less frequent HHT-causing mutations are detected in the MADH4/SMAD4 gene, resulting in a joint condition known as Juvenile Polyposis and HHT (JPHT), where, in addition to HHT symptoms, colon polyps and thoracic aneurysms appear." (PMID 38068462, 2023). "It is well known that germline mutations in MADH4 or BMPR1A (encoding Smad4 or ALK3, respectively) are present in a large number of patients with juvenile polyposis syndrome." (PMID 35693928, 2022). "Although juvenile polyposis patients have been screened for SMAD2 and SMAD3 mutations, only SMAD4 germline mutants are identified as an underlying cause of juvenile polyposis." (PMID 36267157, 2022). "In juvenile polyposis, the ESGE and BSG suggest that oesophagogastroduodenoscopy surveillance starts for asymptomatic individuals with SMAD4 mutation at the age of 18, and with BMPR1A mutation at the age of 25 years." (PMID 34944861, 2021). "One patient, who had juvenile polyposis and HHT (2%), was genetically tested and found to have SMAD4 gene mutation." (PMID 33661356, 2021). "Mutations in SMAD4 (encoding the transcription factor Smad4) have been described in less than 2% of the HHT population and cause juvenile polyposis/HHT overlap syndrome." (PMID 32122373, 2020). "Mutations in SMAD4 are detected in 1 to 2% suspected HHT clinical cases and are also frequently observed in the syndrome of juvenile polyposis (JP) and the mixed syndrome of HHT/JP." (PMID 31910860, 2020). "Mutations in the SMAD4 gene can give rise to a combined syndrome of HHT and juvenile polyposis (JP), the JP-HHT syndrome." (PMID 30251589, 2018). "A subset of patients (2–3%) with a combined syndrome of juvenile polyposis and HHT (defined as JPHT) harbor mutations in the MADH4 (SMAD4) gene." (PMID 25763011, 2015). "For example, loss-of-function mutations in human of either MADH4 (which encodes SMAD4, the downstream transcription factor that mediates the BMP signaling) or BMPRIA are associated with juvenile polyposis syndrome." (PMID 22168923, 2011). "These SMAD4 dosage-dependent transcriptional changes were confirmed and validated in a subset of target genes in intestinal tissues from juvenile polyposis syndrome patients." (PMID 19014666, 2008). "Juvenile Polyposis Syndrome (JPS) is an autosomal dominant disorder characterized by multiple gastrointestinal polyps and an increased risk of cancer, most commonly associated with mutations in the tumor suppressor gene Smad4." (PMID 42193864, 2026). "SMAD4 and BMPR1A are reported to be associated with Juvenile Polyposis Syndrome." (PMID 38898990, 2024).
juvenile polyposis syndrome (continued). "More than one-third of juvenile polyposis syndrome cases arise from de novo mutations and frequently mutated genes include Bone Morphogenetic Protein Receptor 1A (BMPR1A) or Suppressor Mothers Against Decapentaplegic Homolog 4 (SMAD4 or DPC4)." (PMID 39057027, 2024). "In 96% of patients with a definite clinical diagnosis of HHT, a mutation is identified in one of these 3 genes: endoglin (ENG, HHT type 1), activin receptor-like kinase-1 (ACVRL1, HHT type 2), and Mothers against decapentaplegic homolog 4 (SMAD4, juvenile polyposis–HHT overlap syndrome)." (PMID 38492037, 2024). "Juvenile Polyposis – Hereditary Haemorrhagic Telangiectasia overlap syndrome (JP-HHT OMIM175050) was first observed in 1980, although its genetic cause – heterozygous pathogenic SMAD4 loss of function variants – was only identified in 2004." (PMID 38627541, 2024). "In the present case, the patient had no family history of juvenile polyposis, and refused a test for germline mutations in the SMAD4 and BMPR1A genes but was diagnosed with JPST based on physical findings and histopathological features." (PMID 35841758, 2022). "The SMAD4 case also exemplifies the overlapping features of CRC-related syndromes: The patient was highly suspicious of having HNPCC/Lynch Syndrome but ended up with a diagnosis of juvenile polyposis." (PMID 33193653, 2020). "This is not surprising given the known overlap between HHT and Juvenile Polyposis (OMIM# 175050) in patients with SMAD4 mutations." (PMID 32842615, 2020). "Taken together, HHT1 and HHT2 account for more than 80% of all HHT cases, whereas a small number of patients show mutations in SMAD4 (MADH4) or in BMP9 gene (GDF2), which are responsible for less common HHT variants such as a combined syndrome with juvenile polyposis (JP-HHT) and HHT5, respectively." (PMID 30761306, 2019). "In addition, inactivation of BMP receptor 1a (BMPR1A) or Mothers against decapentaplegic homolog 4 (SMAD4) results into human juvenile polyposis syndrome (JPS)." (PMID 28159860, 2017). "Endoglin (ENG, chromosome 9q34), Activin A receptor type II-like 1 (ACVRL1/ACVRL1/ALK1, chromosome 12q13), and MADH4/SMAD4 (chromosome 18q21) mutations cause HHT1 (OMIM 187300), HHT2 (OMIM 600376), and the combined Juvenile Polyposis/HHT (JP/HHT) syndrome (OMIM 175050), respectively." (PMID 28231770, 2017). "Endoglin (ENG, chromosome 9q34), activin A receptor type II-like 1 (ACVRL1/ALK1, chromosome 12q13), and SMAD4 (chromosome 18q21) mutations cause HHT1 (OMIM 187300), HHT2 (OMIM 600376), and the combined Juvenile Polyposis/HHT (JP/HHT) syndrome (OMIM 175050), respectively." (PMID 25674101, 2015). "However, due to the clinical picture screening of the juvenile polyposis genes SMAD4 and BMPR1A was performed on DNA extracted from peripheral blood leukocytes, with Sanger sequencing, including all coding exons and surrounding splice sites (−20 to +20)." (PMID 25705527, 2015). "Indeed, some Smad4 mutations, the common mediator of all R-Smad-dependent TGF-β/BMP family signaling can cause a syndrome that includes both juvenile polyposis and HHT." (PMID 25763012, 2015). "Therefore, we have bred Apc+/1572T animals with Smad4+/Sad, a mouse model for juvenile polyposis previously developed in our laboratory." (PMID 19578404, 2009). "Overall, this study provides new information on understanding the intricate genetic interplay in the context of Smad4 knock-out, offering valuable insights that could inform the identification of potential therapeutic targets for juvenile polyposis and related diseases." (PMID 38891999, 2024). "Hereditary hamartomatous syndromes include Peutz–Jeghers syndrome (PJS, with mutations in LKB1/STK11), PTEN-hamartoma tumor syndrome (PHTS, with mutations in PTEN), and juvenile polyposis syndrome (JPS, with mutations in BMPR1A or SMAD4)." (PMID 38672634, 2024).
juvenile polyposis syndrome (continued). "A small number of cases (approximately 2%) shows a complex clinical picture, including the clinical signs of Juvenile Polyposis Syndrome (JPS) and HHT, and carries mutations in the SMAD4 gene (18q21.2, OMIM 600993)." (PMID 36810341, 2023). "Mutations in Bone Morphogenetic Protein (BMP) Receptor (BMPR)1A and SMAD4 are detected in 50% of juvenile polyposis syndrome (JPS) patients, who develop stroma-rich hamartomatous polyps." (PMID 36326956, 2023). "Germline mutations in SMAD4 and BMPR1A genes have been identified to cause juvenile polyposis syndrome (JPS)." (PMID 35320498, 2022). "Among the atypical cases were two individuals in whom the panel-based testing identified a gene mutation in SMAD4 indicating a diagnosis of juvenile polyposis; yet the polyp types reported on the TRF in one case did not include juvenile polyps and in the other case no history of polyps was reported." (PMID 24506336, 2014). "Moreover, a combined phenotype of HHT and Juvenile Polyposis is recognized as the JPHT syndrome, related to mutations in MADH4 gene (18q21.1; OMIM*600993), coding for SMAD4, the common mediator of TGF-β/BMPs signalling, involved in transcriptional activation of as yet unidentified target genes." (PMID 22028876, 2011). "Regarding juvenile polyposis syndrome (JPS), a rare autosomal dominant disorder, genetic testing reveals aberrant Smad4 expression, which serves as a biomarker for rapid diagnosis of this disease." (PMID 40969268, 2025). "Research on Juvenile Polyposis Syndrome (JPS) has shown that SMAD4 IHC, as an indicator of SMAD4 gene status, can serve as a preferred screening method for molecular diagnosis, which is crucial for distinguishing CRC from other types of intestinal diseases." (PMID 39164192, 2024). "A small subset of HHT patients (~ 4%) exhibit haploinsufficiency of Mothers against decapentaplegic homolog 4 (SMAD4, JP/HHT) and commonly present with juvenile polyposis syndrome (JP)." (PMID 29460088, 2018). "Single mutations are detected in Endoglin (ENG; HHT1) (MIM # 131195), Activin Receptor-Like Kinase 1 (ACVRL1/ALK1; HHT2) (MIM # 601284), or MADH4/SMAD4 (JHPT, a combined syndrome of juvenile polyposis and HHT)." (PMID 26176610, 2015). "HHT is transmitted as an autosomal dominant condition due to a single mutation in Endoglin (ENG; HHT1), Activin Receptor-Like Kinase 1 (ACVRL1/ALK1; HHT2), or MADH4/SMAD4 (JHPT, a combined syndrome of juvenile polyposis and HHT)." (PMID 24267784, 2013). "In 90% of patients with a definite clinical diagnosis of HHT, a mutation is identified in one of these three genes: endoglin (ENG, HHT type 1), activin receptor-like kinase-1 (ACVRL1, HHT type 2), and Mothers against decapentaplegic homolog 4 (SMAD4, juvenile polyposis–HHT overlap syndrome)." (PMID 39597796, 2024). "Finally, another gene, MADH4/SMAD4, has been identified as being responsible for a combined syndrome, including HHT and juvenile polyposis." (PMID 35683441, 2022). "Recent investigations reported SMAD4 and BMPR1A as genes responsible for juvenile polyposis." (PMID 30043121, 2018). "In addition to these two genes, alteration of SMAD4 has been identified in a subset of patients with HHT and juvenile polyposis (approximately 2% of cases), a condition termed PJ-HHT syndrome, in which juvenile polyps and anemia are the predominant clinical features." (PMID 36079173, 2022). "This mixed polyposis is seen in BMPR1a DCV carriers but not in SMAD4 DCV carriers, who typically present with homogenous juvenile polyposis." (PMID 37400896, 2023).
gastric cancer (99 papers, 2008 to 2025). A primary or metastatic malignant neoplasm involving the stomach. "Considering that SMAD4 is a target of miR-146a, it is possible that miR-146a overexpression, as a consequence of the rs2910164 C allele, inhibits apoptosis via the downregulation of SMAD4, as occurs in gastric cancer." (PMID 40277937, 2025). "Several studies have indicated that the loss of SMAD4 is frequent in multiple cancers, such as lung, colon, breast, and gastric cancers." (PMID 40277937, 2025). "Initially, EBV-miRNA-BART6-5p and its target gene SMAD4 expression were assessed in EBV-associated gastric cancer tissues and cell lines." (PMID 38686046, 2024). "The incidence of cancer in patients with JPS is 11%–86%, with a significantly higher incidence of gastric cancer in those with SMAD4 mutations (10.3%); preventive gastrectomy is recommended in such cases." (PMID 38191939, 2024). "Although the correlation between genotype and phenotype is still under research, SMAD4 mutations have been linked to gastric polyps, gastric cancer, and hereditary hemorrhagic telangiectasia (HHT)." (PMID 38975412, 2024). "SMAD4 DCVs are associated with higher gastric polyp numbers, massive gastric polyposis, and thus, partial or total gastrectomy and gastric cancer." (PMID 38066625, 2023). "7/17 JPS patients with SMAD4 variants had gastric cancer in a study by Aretz and colleagues, compared to 0/13 for BMPR1A carriers." (PMID 38066625, 2023). "We present a clinical case of early onset gastric cancer associated with a frameshift mutation in the gene SMAD4." (PMID 36447760, 2022). "SMAD1, SMAD2, and SMAD4 are associated with favorable OS in the first and third stage of gastric cancer." (PMID 34138687, 2021). "The SNP rs12456284 locates 3′ UTR region of the Smad4 gene, was predicted to influence the potential miRNA binding, and downregulate the gene expression with Smad4 associated with gastric cancer." (PMID 34307117, 2021). "This study shows that high expression level of SMAD1, SMAD2, and SMAD4 is associated with favorable OS of gastric cancer patients." (PMID 34138687, 2021). "The risk of CRC and gastric cancer is increased with the risk of gastric polyposis, gastric cancer being highest in SMAD4 carriers." (PMID 34620187, 2021). "Analysis showed that high expression levels of SMAD1, SMAD2, and SMAD4 are associated with a better survival rate of gastric cancer patients, whereas SMAD3, SMAD5, SMAD6, SMAD7 and SMAD9 are associated with poor prognosis." (PMID 34138687, 2021). "SMAD4 protein expression is lost in gastric cancer cells and loss of expression in primary gastric adenocarcinomas are associated with poor survival." (PMID 32807122, 2020). "At present, the loss of the nuclear expression of SMAD4 has been described in the progression of gastric cancer." (PMID 28512631, 2017). "In conclusion, EBV-encoded BARF1 promotes stomach cancer cell proliferation through a mechanism involving the upregulation of NFκB and miR-146a and the downregulation of SMAD4." (PMID 27438138, 2016). "Kaplan–Meier survival analysis revealed that miR-558 and Smad4 were associated with unfavourable and favourable outcome of gastric cancer patients, respectively." (PMID 27685626, 2016). "The results of the present study indicate that EBV-encoded BARF1 promotes cell proliferation in stomach cancer through a mechanism involving NFκB and miR-146a-5p upregulation and SMAD4 downregulation." (PMID 27438138, 2016). "In conclusion, EBV-encoded BARF1 promotes cell proliferation in stomach cancer by upregulating NFκB and miR-146a and downregulating SMAD4, thereby contributing to EBV-induced stomach cancer progression." (PMID 27438138, 2016). "Our findings reveal the mechanisms of HPSE gene expression associated with gastric cancer progression, and suggest that miR-558 and Smad4 are potential therapeutic targets of gastric cancer." (PMID 27685626, 2016).